MS4A6A (membrane spanning 4-domains A6A)
Description:
May be involved in signal transduction as a component of a multimeric receptor complex.
Synonyms: 4SPAN3; CD20L3; MS4A6; CDA01; MSTP090; 4SPAN3.2; MST090
Tractability: Antibody: UniProt predicts a signal peptide or a membrane-spanning region; its Gene Ontology location is reachable by antibodies, with medium confidence.
Gene: Protein-coding gene on chromosome 11 (60,170,074 to 60,184,666, reverse strand). Ensembl gene ENSG00000110077.
Subcellular location: Membrane
Subcellular location (Human Protein Atlas): Vesicles
Gene Ontology:
Molecular function: protein binding
Biological process: cell surface receptor signaling pathway
Cellular component: trans-Golgi network; plasma membrane; membrane
Genetic constraint (gnomAD): Loss-of-function variants: 18 observed, 20.06 expected, observed/expected ratio (o/e) 0.9, 90% interval 0.62 to 1.33. The upper end of that interval is the gene's LOEUF score, 1.33, which puts it in group 5 of 6, group 1 being the genes least tolerant of losing a copy. Missense variants: 268 observed, 268.04 expected, observed/expected ratio (o/e) 1, 90% interval 0.9 to 1.11. Synonymous variants: 107 observed, 109.99 expected, observed/expected ratio (o/e) 0.97, 90% interval 0.83 to 1.14.
Homologues: Orthologues: chimpanzee MS4A6A (95% identical), macaque MS4A6A (90% identical), mouse Ms4a6d (53% identical), rat Ms4a6a (53% identical), rat Ms4a6b (52% identical), mouse Ms4a6b (52% identical), rat Ms4a6bl1 (51% identical), rat Ms4a6bl1 (48% identical), mouse Ms4a6c (47% identical), zebrafish si:dkey-77f5.10 (22% identical), zebrafish ms4a17a.10 (21% identical), zebrafish ms4a17a.16 (21% identical), and 22 more. Paralogues in human: MS4A6E (52% identical), MS4A7 (36% identical), MS4A12 (26% identical), MS4A15 (24% identical), MS4A4A (24% identical), MS4A8 (23% identical), MS4A3 (22% identical), MS4A1 (21% identical), MS4A5 (21% identical), MS4A2 (20% identical), MS4A18 (20% identical), MS4A10 (19% identical), and 4 more.
Diseases named in the same sentence as MS4A6A in open-access papers:
MS4A6A is named in the same sentence as 32 diseases in open-access papers, as found by Europe PMC text mining. Sharing a sentence is not in itself a finding about the gene and the disease. The quoted sentences say what the papers report.
Alzheimer disease (16 papers, 2015 to 2026). A progressive, neurodegenerative disease characterized by loss of function and death of nerve cells in several areas of the brain leading to loss of cognitive function such as memory and language. "An application to Alzheimer's disease also reveals cell-subtype-specific associations, including MS4A6A in the disease-associated microglial subtype and PPP1R37 in the inflammatory microglial subtype." (PMID 41820391, 2026). "An application to Alzheimer’s disease also revealed cell-subtype-specific associations, including MS4A6A in disease-associated microglia and PPP1R37 in both inflammatory microglial and astrocyte subtypes." (PMID 41256005, 2025). "Genes such as SLC1A3, FOXP1, and MS4A6A, associated with inflammatory response, and microglia in aging and Alzheimer's disease, had positive average coefficients among the microglia clock feature genes." (PMID 40878446, 2025). "This association was modified by allelic variants in genes ABCA7, CLU, BDNF and MS4A6A that have been previously linked to Alzheimer’s disease." (PMID 37658429, 2023). "Our TWAS analyses provide evidence that expression of MS4A4A and MS4A6A in CD14+ monocytes is relevant to Alzheimer’s disease risk, although conditional analyses are unable to conclusively localise the signal to either of these genes." (PMID 33959712, 2021). "Of other DEGs, membrane spanning 4-domains A6A (MS4A6A) has been reported to associate with Alzheimer’s disease, and the expression of MS4A6A could be down-regulated by the immunosuppressive domain (gp41) of HIV-1." (PMID 30626383, 2019). "Membrane-spanning 4-domains, subfamily A, member 6A (MS4A6A) has been identified as susceptibility loci of Alzheimer's disease (AD) by several recent genome-wide association studies (GWAS), whereas little is known about the potential roles of these variants in the brain structure and function of AD." (PMID 27244883, 2016). "Research on MS4A6A is mainly focused on Alzheimer’s disease, and there are also current studies showing that it can be used as a prognostic marker for tumors." (PMID 34195091, 2021). "STX3, one of the novel TWAS significant genes was dropped after conditional analysis along with three of the genes in Alzheimer’s disease risk loci: FNBP4, MYBPC3 and MS4A6A." (PMID 33959712, 2021). "MS4A6A appears to be strongly associated with Alzheimer’s disease; however, the MS4A6A gene has not been investigated." (PMID 37578930, 2023). "Clusters M-D and M-G express SEPP1 and MS4A6A, macrophage markers that have been studied in a variety of contexts including atherosclerotic plaque formation, tumor infiltration, and Alzheimer’s disease." (PMID 34554929, 2021). "Notably, several Alzheimer’s disease (AD)-associated genetic risk variants—including APOE ε4, TREM2 R47H (rs75932628), CD33 rs3865444-C, INPP5D regulatory variants, MS4A6A locus variants, and PLCG2 P522R (rs72824905)—are enriched in microglia and influence their functional state." (PMID 40934003, 2025). "These include genes such as NUSAP1 and MS4A6A that are associated to glomerulonephritis, an IgA nephropathy; GPBAR1 that is highly expressed in intestinal monocytes of patients with inflamed Crohn's disease, and; SYNJ1 and PLD3 that are both associated to Parkinson's disease and Alzheimer's disease." (PMID 26338775, 2015).
glioma (5 papers, 2022 to 2024). A benign or malignant brain and spinal cord tumor that arises from glial cells (astrocytes, oligodendrocytes, ependymal cells). "In the immune microenvironment of glioma, MS4A6A exhibits unique expression characteristics in macrophages." (PMID 39470579, 2024). "In our study, we used public cancer databases to analyse data and discovered that MS4A6A is highly expressed in glioma tissues compared to normal tissues." (PMID 39470579, 2024). "Here, we show that MS4A6A is upregulated in glioma tissues, resulting in unfavorable clinical outcomes and poor responses to adjuvant chemotherapy." (PMID 36119086, 2022). "RT-qPCR and IHC staining using tissues from healthy controls and LGG and GBM patients validated that MS4A6A is overexpressed in glioma." (PMID 36119086, 2022). "Here, we report that MS4A6A is hypomethylated and overexpressed in glioma tissue at both transcriptional and protein levels, which is related to a significant decrease in overall survival (OS)." (PMID 36119086, 2022). "Elevated expression of MS4A6A was found in glioma patients with a mean age > 43 years, demonstrating the tight association of MS4A6A expression with the aging process." (PMID 36119086, 2022). "In summary, these findings indicate that MS4A6A is overexpressed in glioma and that hypomethylation is the major epigenetic mechanism leading to overexpression of MS4A6A in glioma." (PMID 36119086, 2022). "For further analysis of the main macrophage subpopulations in which MS4A6A is involved, 10 scRNA-seq glioma samples were introduced." (PMID 36119086, 2022). "MS4A6A plays an important role in prognostic, immune and biological functions in gliomas." (PMID 39470579, 2024). "In conclusion, MS4A4A, MS4A4E, MS4A6A, MS4A7, TMEM176A, and TMEM176B may act as potential diagnostic or prognostic biomarkers in glioma and play a role in forming the immune microenvironment in gliomas." (PMID 35734424, 2022). "To gain deep insight into whether stratification based on MS4A6A expression impacts the glioma response to immunotherapy, we first explored and validated the high degree of correlation between MS4A6A and checkpoints at the transcriptome level." (PMID 36119086, 2022). "In summary, great efforts have been made to explore the biology of MS4A6A in glioma." (PMID 36119086, 2022). "We comprehensively analyzed mechanisms of MS4A6A dysregulation in glioma, highlighting its negative influence on clinical outcomes and further illustrating the differences in macrophage infiltration in association with MS4A6A expression." (PMID 36119086, 2022). "Interestingly, MS4A6A is expressed in M2 macrophages and correlates with macrophage infiltration, unfavorable clinical outcome, and poor responses to adjuvant chemotherapy in glioma patients." (PMID 37791581, 2023). "DNA methyltransferases DNMT3B, DNMT3A, and DNMT1 were comparatively overexpressed in the MS4A6A high expression subgroup, which might be the reason for MS4A6A hypomethylation in glioma tissues, leading to insight into upregulated mechanisms of MS4A6A in glioma." (PMID 36119086, 2022). "Using bioinformatics analysis methods based on the data from public databases, we found that the expression of MS4A4A, MS4A4E, MS4A6A, MS4A7, TMEM176A, and TMEM176B was significantly overexpressed in glioma tissues compared with that of normal tissues." (PMID 35734424, 2022). "In TCGA data, the expression level of MS4A4A, MS4A4E, MS4A6A, MS4A7, TMEM176A, and TMEM176B in IDH wild-type glioma was elevated." (PMID 35734424, 2022). "Finally, GSEA was conducted for glioma samples, and GOBP: innate immune response and GOBP: Toll-like signaling pathway were enriched in the MS4A6A high expression group." (PMID 36119086, 2022).
glioma (continued). "Moreover, according to K-M plots, the survival differences were still obvious after grouping by MS4A6A expression and clinicopathologic subgroups (log-rank test, p < 0.001), demonstrating that the MS4A6A expression level might play an important role in glioma OS classification." (PMID 36119086, 2022). "Therefore, these preliminary results indicate that MS4A4A, MS4A4E, MS4A6A, MS4A7, TMEM176A, and TMEM176B are potential prognostic factors for glioma." (PMID 35734424, 2022). "In TCGA data, the expression level of MS4A4A, MS4A4E, MS4A6A, MS4A7, TMEM176A, and TMEM176B in 1p/19q non-codel glioma was elevated." (PMID 35734424, 2022).
dementia (3 papers, 2015 to 2023). Loss of intellectual abilities interfering with an individual's social and occupational functions. "There is prior evidence of increased expression of ABCA7, BIN1, and MS4A6A in LOAD brains, and increased ABCA7 expression is associated with clinical dementia rating, with higher expression being associated with more advanced cognitive decline." (PMID 26101835, 2015).
ovarian carcinoma (3 papers, 2020 to 2023). A malignant neoplasm originating from the surface ovarian epithelium. "In ovarian cancer, MS4A6A was associated with pathological grade and might act as a surface marker for M2 macrophages." (PMID 33169786, 2020). "CD163, MS4A4A and MS4A6A are surface markers for M2 macrophages, and higher MS4A4A and MS4A6A levels were associated with a poorer prognosis in ovarian cancer patients." (PMID 33323552, 2020).
glioblastoma (2 papers, 2025). The most malignant astrocytic tumor (WHO grade IV). "MS4A6A, a key regulator of microglial activation and immune response, plays a role in neurodegenerative diseases like Alzheimer's and glioblastoma." (PMID 41239018, 2025). "The gene MS4A6A, a member of the membrane‐spanning four‐domain subfamily A (MS4A) gene family, has been implicated in various pathological conditions including neurodegenerative diseases and glioblastoma by modulating immune responses." (PMID 40219815, 2025).
Brain atrophy (1 paper, 2021). Partial or complete wasting (loss) of brain tissue that was once present. "The important association between MS4A6A and PI (57.14% had differential association with MS4A6A) might indicate the involvement of PI mediating MS4A6A’s effect on brain atrophy." (PMID 34092785, 2021).
breast carcinoma (1 paper, 2022). "Furthermore, scRNA-seq of breast cancer indicated that the angiogenesis factors plasminogen activator, urokinase receptor (PLAUR) and IL-8 were expressed in TAMs in addition to M2-type genes, such as CD163, membrane spanning 4-domains A6A (MS4A6A), and transforming growth factor beta-1 (TGF-β1)." (PMID 36154923, 2022).
breast ductal carcinoma in situ (1 paper, 2024). "We also detected the expression of MS4A6A in tissues from breast ductal carcinoma in situ (DCIS), and multicolor fluorescence staining revealed that MS4A6A is expressed mainly in infiltrated CD68+ macrophages." (PMID 39717774, 2024).
Cerebral atrophy (1 paper, 2015). Atrophy (wasting, decrease in size of cells or tissue) affecting the cerebrum. "Expression of the top five differentially expressed genes found by GWAS - MS4A6A, CD2AP, INPP5D, MEF2C and CLU – all have good correlation with Braak stage and cerebral atrophy." (PMID 26202100, 2015).
epilepsy (1 paper, 2025). A brain disorder characterized by episodes of abnormally increased neuronal discharge resulting in transient episodes of sensory or motor neurological dysfunction, or psychic dysfunction. "Our results revealed a marked upregulation of MS4A4A, MS4A6A, MS4A7, and MS4A14 in lesional tissues of FEAT epilepsy patients relative to perilesional tissues." (PMID 40349168, 2025).
prion disease (1 paper, 2024). A transmissible disease that is caused by a protein that is able to induce abnormal folding of normal cellular proteins, leading to characteristic spongiform brain changes, which are associated with neuronal loss without an inflammatory response. "Additionally, our findings from various algorithms showed that MS4A6A is strongly associated with apoptosis, the T cell receptor signalling pathway, prion disease and other pathways." (PMID 39470579, 2024).
tumor (11 papers, 2017 to 2025). "In this study, we identify MS4A6A as an immune-related prognostic biomarker that delineates a subset of tumor-associated macrophages enriched in inflammatory and immunoregulatory programs." (PMID 41515934, 2025). "We also identified that MS4A6A expression positively correlates with genes related to tumour-associated macrophages, which induce macrophage infiltration and immune suppression." (PMID 38864705, 2024). "Our research demonstrated that MS4A6A is positively correlated with most immune cells, particularly tumour‐associated fibroblasts and M1 and M2 macrophages." (PMID 39470579, 2024). "MS4A6A was reported to be highly expressed in putative Tumor-associated macrophages (TAMs) populations." (PMID 33604283, 2020). "To investigate therapeutic options to counteract MS4A6A‐mediated tumour promotion, we conducted cMAP analysis." (PMID 39470579, 2024). "To determine whether MS4A6A expression is elevated in tumours and its clinical significance for GBM, we analysed data from TCGA‐GBM and TCGA‐GBM combined with GTEx, respectively." (PMID 39470579, 2024). "MS4A6A might be expressed more frequently on the surface of antigen-presenting cells in the tumor microenvironment." (PMID 37578930, 2023). "In addition, we found that MS4A6A expression also correlated significantly with CD8+ and CD4+ T cells, suggesting the relevance of MS4A6A in tumor killing." (PMID 37578930, 2023). "However, the precise role of MS4A6A in cancer progression remains unclear, and the relationship between MS4A6A expression in tumor tissues and immune cell infiltration needs further investigation." (PMID 39717774, 2024). "In the TCGA-LUAD dataset, we observed that MS4A6A expression was positively correlated with immune cell infiltration in the tumor microenvironment, especially macrophages, dendritic cells, and multiple immune checkpoints, suggesting that MS4A6A could be a potential biomarker for ICB therapy." (PMID 37578930, 2023). "Our study revealed that MS4A6A can function as a prognostic marker in various malignant tumors, including DCIS, because of its role in tumorigenesis and tumor immunity." (PMID 39717774, 2024). "According to the tumor grades, in TCGA database, compared with WHO II and III, the transcription levels of MS4A4A, MS4A4E, MS4A6A, MS4A7, TMEM176A, and TMEM176B were the highest in WHO IV." (PMID 35734424, 2022).
neurodegenerative disease (7 papers, 2022 to 2025). A disorder of the central nervous system characterized by gradual and progressive loss of neural tissue and neurologic function. "This study aimed to investigate the potential role of MS4A6A, a gene associated with aging and neurodegenerative diseases, in GBM and its potential as a prognostic biomarker and therapeutic target." (PMID 39470579, 2024). "Membrane spanning 4-domains A6A (MS4A6A) has also been shown to be associated with aging-related neurodegenerative diseases." (PMID 38129488, 2023). "MS4A6A has been recognized as being associated with aging and the onset of neurodegenerative disease." (PMID 36119086, 2022). "MS4A6A has been linked to aging and the progression of neurodegenerative diseases." (PMID 39470579, 2024). "MS4A6A is recognized to be associated with aging and neurodegenerative diseases, and bioinformatic analysis has revealed its high expression in DN, but the exact mechanism is unknown." (PMID 38764052, 2024). "In addition, MS4A6A has been shown to be associated with neurodegenerative diseases and disease pathobiology, but whether it is involved in the regulation of GBM and its mechanisms remain unelucidated." (PMID 39470579, 2024). "Previous studies in neurodegenerative disease contexts identified MS4A6A and its murine homolog Ms4a6d as microglia-specific genes that restrain inflammation and support phagocytic functions through NF-κB regulation." (PMID 41515934, 2025). "Thus, MS4A6A is a critical target for therapeutic strategies in MS and other neurodegenerative diseases." (PMID 41239018, 2025).
cancer (6 papers, 2007 to 2024). A tumor composed of atypical neoplastic, often pleomorphic cells that invade other tissues. "The results indicate that TTNPB may reverse the molecular signature associated with MS4A6A dysregulation, counteracting its pro‐cancer effects." (PMID 39470579, 2024). "Therefore, we investigated MS4A6A expression characteristics and immune checkpoint-associated gene expression in various cancer types." (PMID 37578930, 2023). "Notably, we observed that MS4A6A is positively correlated with genes associated with immune checkpoints in LUAD and 32 other cancer types." (PMID 37578930, 2023). "Notably, we observed that the MS4A6A gene was positively correlated with these immune-related genes in LUAD as well as in the other 32 cancers." (PMID 37578930, 2023).
MS4A6A also shares sentences with these, for which no sentence is quoted: astrocytoma (1 paper); cognitive decline (1); Crohn disease (1); esophageal cancer (1); gastric cancer (1); glomerulonephritis (1); hepatocellular carcinoma (1); hippocampal atrophy (1); IgA nephropathy (1); infection (1); kidney disease (1); latent infection (1); lung adenocarcinoma (1); lung carcinoma (1); lung squamous cell carcinoma (1); neonatal diabetes mellitus (1); neurological disease (1); Parkinson disease (1).